MDM2 (MDM2 proto-oncogene)
Diseases named in the same sentence as MDM2 in open-access papers (continued):
Sharing a sentence is not in itself a finding about the gene and the disease.
neuroblastoma (continued). "Concerning neuroblastoma, consistent data indicate that MNA cells are strikingly sensitive to death induced by MDM2-antagonist, while cell growth inhibition might be the preferential outcome in MYCN single copy neuroblastoma." (PMID 23091802, 2012). "Because increased activity of MYCN in stage 4s-NA or c-MYC in stage 4-NA tumors should both result in high expression of shared target genes compared to localized-NA neuroblastomas, we analyzed known direct MYCN/c-MYC target genes, namely MDM2, DKC1, and PTMA, in neuroblastoma subtypes." (PMID 18851746, 2008). "Specifically, MDM2 was found to upregulate MYCN RNA levels and MYCN translation in NB1691 and SK-N-SH neuroblastoma cells and in RB176 and Y79 retinoblastoma cells, effects attributed to MYCN RNA stabilization and ribosomal loading in the neuroblastoma setting." (PMID 33425720, 2020). "Thus, as in retinoblastoma and neuroblastoma, high MDM2 was needed to maintain high-level MYCN but not MYC expression in SCLC cell lines." (PMID 33425720, 2020). "This study suggests that SP141 warrants further investigation as an MDM2 antagonist, particularly in combination with other agents currently used to treat neuroblastoma, such as mTOR or ALK inhibitors, to provide improved anticancer activity against neuroblastomas with different genetic backgrounds." (PMID 33291373, 2020). "We used DSS to treat either the neuroblastoma cell line NB-1691 and LA1-55N, having endogenous MDM2 expression, or SK-N-SH having a transfected MDM2 to study MDM2 homodimerization and to evaluate whether homodimerization affects the level of MDM2 protein expression." (PMID 25888903, 2015).
neuroblastoma (continued). "Here, we report that intrinsically high MDM2 expression is required for high-level expression of MYCN, but not for expression of MYC, in retinoblastoma, neuroblastoma, small cell lung cancer, and medulloblastoma cells." (PMID 33425720, 2020). "Conversely, MYCN KD was found to downregulate MDM2 in IMR-32 neuroblastoma cells but not in NB-1691 and NB-1643 neuroblastoma or RB176 retinoblastoma cells, implying that MYCN dependent MDM2 expression is cell line-specific." (PMID 33425720, 2020). "Nutlin-3 and MI-63, both MDM2 inhibitors, have more effectively suppressed proliferation of MYCN-amplified neuroblastoma cells compared to cells lacking MYCN amplifications." (PMID 29416773, 2018). "In addition, in neuroblastoma xenograft models, SP141 inhibited MDM2 expression and suppressed tumor growth without any host toxicity at the effective dose." (PMID 33291373, 2020).
colorectal cancer (108 papers, 2008 to 2026). A primary or metastatic malignant neoplasm that affects the colon or rectum. "Specifically in colon cancer, increases in MDM2 protein expression and gene amplification are observed, which is associated with increased colorectal cancer risk and can be used as a prognostic marker." (PMID 30271790, 2018). "Our results showed that miR-1827 is frequently down-regulated in colorectal cancer, and its expression is negatively associated with MDM2 expression in colorectal cancer." (PMID 26840028, 2016). "miR-1827 is frequently down-regulated and its expression is negatively associated with MDM2 expression in human colorectal cancer." (PMID 26840028, 2016). "Decreased miR-1827 expression is associated with high MDM2 expression and poor prognosis in colorectal cancer." (PMID 26840028, 2016). "Furthermore, in colorectal cancer, the presence of liver metastasis was significantly associated with low MDM2 mRNA expression in the primary tumor, and MDM2 amplification negatively correlated with occurrence of distant metastases." (PMID 26416355, 2015). "The study aim was to apply murine double minute 2 (MDM2)-siRNA to a biodegradable siRNA delivery vector, ternary complex, for treating colorectal cancer peritoneal dissemination." (PMID 41009451, 2025). "Peritoneal injection of this ternary complex that included MDM2-siRNA would be useful for treatment of colorectal cancer peritoneal dissemination." (PMID 41009451, 2025). "Cellular uptake of the ternary complex and suppressive effect on MDM2-mRNA were determined in a mouse colorectal cancer cell line." (PMID 41009451, 2025). "For example, the combination of apatinib and piperine inhibited HCT-116 colorectal cancer cells by regulating MDM-2 gene expression." (PMID 39342176, 2024). "High expression of MDM2/CY and DUSP6/SN was significantly associated with a higher risk of colorectal cancer with OR ranges of 5.95–10.62 and 2.14–3.82, respectively." (PMID 36672653, 2023).
colorectal cancer (continued). "More interestingly, it has been shown that elevated levels of circMDM2 in response to DNA damage in colorectal cancer (CRC) cell lines lowered MDM2 protein production, suggesting that this circular isoform is a derivative of the original pre-mRNA." (PMID 36900344, 2023). "Inhibition of UBA2 expression reduces the proliferation of colorectal cancer and gastric cancer cells regulating cyclinB1, B cell lymphoma-2, and E3 ubiquitin-protein ligase MDM2." (PMID 33008487, 2020). "We discovered a novel mechanism of action of DIM, that it directly inhibits MDM2 in multiple colorectal cancer (CRC) cell lines." (PMID 32629830, 2020). "For example, MDM2 DNA is found to be amplified in different types of cancers, including colorectal cancer." (PMID 26840028, 2016). "A recent study reported that miR-194 was decreased and associated with tumor size and tumor differentiation in colorectal cancer, overexpression of miR-194 suppresses tumor growth by regulating the MAP4K4/c-Jun/MDM2 signaling pathway." (PMID 26909612, 2016). "The expression of MDM2 is inversely correlated with RASSF10 in primary colorectal cancer (P < 0.05)." (PMID 25638156, 2015). "In summary, our results in this study demonstrated that miR-339-5p negatively regulates MDM2 in colorectal cancer cells." (PMID 25193859, 2014).
colorectal cancer (continued). "MiR-339-5p mimic greatly reduced MDM2 protein levels in all these four colorectal cancer cell lines." (PMID 25193859, 2014). "Some genetic alterations, such as that of the promoter of the MDM2 oncogene, are able to modify the age of onset of colorectal cancer and probably differentiate prognosis." (PMID 18026187, 2008). "In spite of the widespread involvement of LIF in the STAT3 pathway found in oncological studies, other oncogenic pathways associated with LIF exist, for instance, the LIF/p‐AMPK signaling pathway in HCC, and the LIF/STAT3/ID1/ MDM2 signaling pathway in colorectal cancer." (PMID 40416597, 2025). "Therefore, in vivo tumor-growth inhibition by the MDM2-siRNA complex was evaluated in colorectal cancer peritoneal dissemination model mice, which were intraperitoneally injected with Colon26/Luc cells." (PMID 41009451, 2025). "Similarly, the survival time of the colorectal cancer peritoneal dissemination model mice was prolonged only by administering the MDM2-siRNA complex." (PMID 41009451, 2025). "In our study, none of the genotypes at rs2279744 in MDM2 were found to be associated with colorectal cancer (CRC)." (PMID 39242607, 2024). "Moreover, in cancer cell lines with an unmethylated ARF promoter, MDM2 was found to be localized in the nucleus, whereas a colorectal cancer cell line with a hypermethylated ARF promoter revealed MDM2 to be localized in the cytoplasm as well." (PMID 34065345, 2021). "Here, we report our new findings that DIM directly inhibits MDM2 in colorectal cancer cells." (PMID 32629830, 2020).